NLRP3 (NLR family pyrin domain containing 3)
Diseases named in the same sentence as NLRP3 in open-access papers (continued):
Sharing a sentence is not in itself a finding about the gene and the disease.
cancer (continued). "Among the most studied inflammatory processes, the NLRP3 inflammasome is the best characterized, and it has attracted attention for its involvement in several cancer types, although its role is still being debated and controversial." (PMID 35884397, 2022). "The involvement of NLRP3 inflammasome in inflammation-related diseases and cancers makes it an attractive therapeutic target." (PMID 36619871, 2022). "Further studies revealed that MIR503HG inhibited NETs-triggered NSCLC cell metastasis in an NF-κB/NLRP3-dependent manner, as overexpression of NF-κB or NLRP3 impaired the suppressive effect of MIR503HG on NETs-induced cancer cell metastasis." (PMID 35707534, 2022). "In recent studies, NLRP3 (NLR family pyrin domain containing protein 3) inflammasome has been observed to take part in inflammation related to cancer and tumor progression." (PMID 36364001, 2022). "The first showed that the components of the NLRP3 inflammasome were highly expressed in these cell lines and correlated tightly with the characteristic markers of cancer stem cells of head and neck SCC." (PMID 36325196, 2022). "Considering that some plant lectins are known to induce formation of the NLRP3 inflammasome in immune and cancer cells, we addressed the role of pyroptosis in mediating cell death in MC-38 cells treated with WGA, MAL I and AAL." (PMID 35222379, 2022). "Chitin and its derivatives are able to upregulate and downregulate the effect of the NLRP3 inflammasome based on its preparation, and these different reactions can be utilised to successfully target a broad range of cancers." (PMID 35877745, 2022). "This is relevant in the context of cancer because inflammation promoted by the NLRP3 inflammasome can lead to cancer." (PMID 35630688, 2022). "We used RNAscope and IHC to detect Fn infection, NLRP3 expression and MDSCs infiltration in cancer tissues and adjacent tissues collected from 258 ESCC patients treated with conventional TP chemotherapy after surgery." (PMID 35435776, 2022). "In this study, we aimed to investigate the impact of Az, a macrolide, and ceftriaxone, a lactamide, antibiotics on NLRP3 expression in LPS-primed cancer cells." (PMID 36012769, 2022). "Cancer-derived exosomal tripartite motif-containing 59 activates the NLRP3 inflammasome in macrophages by ubiquitination and degradation of abhydrolase domain containing 5, which facilitated lung cancer growth and metastasis in vivo." (PMID 35739593, 2022). "Further highlighting the complex functions of NLRP3 in cancer is a study demonstrating that Nlrp3-/- mice are protected against experimentally induced inflammation-associated skin carcinogenesis." (PMID 35299732, 2022). "The possibility of using chitin and its derivatives as a potential anti-cancer drug due to its effects on the NLRP3 inflammasome and its components is underexplored." (PMID 35877745, 2022). "Brownish yellow granules were present in the cytoplasm of cancer cells at the same position in sequential sections, indicating positive NLRP3 expression, while was the corresponding adjacent tissues were mostly negative for NLRP3 expression (p < 0.05)." (PMID 35435776, 2022). "Hydrogen treatment of these cell lines showed an increase in mitochondrial ROS which facilitated NLRP3-dependent pyroptosis of the cancer cells and showing a protective effect on normal epithelial endometrial cells." (PMID 35877745, 2022). "The contrasting roles of NLRP3 inflammasome can be due to multiple factors such as type, heterogeneity and stage of cancer cells, or TME characteristics." (PMID 35530309, 2022). "Prognostic analysis for OS, DSS, and PFS revealed that hypomethylation of DLAT, FDX1, MTF1, NLRP3, and PDHA1 was associated with low survival in most cancers, whereas hypermethylation of FDX1 and PDHB was associated with low survival in UVM(P < 0.05)." (PMID 36387247, 2022).
cancer (continued). "As a result, the Mn and Fe ions were released to elicit the Fenton-like reaction for the rapid ROS generation, which synergistically activated the NLRP3 inflammasomes to induce cancer cell pyroptosis." (PMID 36612023, 2022). "Different studies have reported the regulation of NLRP3 by the ER trigging pathway involved in cancer progression as the Wnt/β-catenin/CyclinD1 signaling pathway." (PMID 35745570, 2022). "Pharmacological reduction of NLRP3 activity has been suggested as a tool to alleviate doxorubicin-induced cardiotoxicity while preserving or even improving its anti-cancer activity." (PMID 35530309, 2022). "In cancer, NLRP3 and IL-1ß drive cancer progression by different means, involving promotion of tumorigenesis, angiogenesis, immunosuppression, and metastasis." (PMID 36466820, 2022). "In this study, we observed that miR-223-3p suppressed the pro-cancer effects of NLRP3 on the invasion and migration of NSCLC cells." (PMID 36276078, 2022). "In HCC, inhibition of NLRP3 promotes the killing effect of T cells to cancer cells by repressing the expression of immune checkpoints." (PMID 36389791, 2022). "The NLRP3 inflammasome complex plays a key role during the development of various human malignancies, including different cancer types." (PMID 35745570, 2022). "Further, ssGSEA analysis associated NLRP3+ and INHBA+ macrophage subsets with multiple pathways related to carcinoma, angiogenesis, wound healing, and T cell exhaustion; all classical hallmarks of efferocytosis." (PMID 36439171, 2022). "Downregulated expression of NLRP3 inflammasome in HCC correlated with the aggravation of carcinoma, while reconstitution of NLRP3 inflammasome reversed the malignant phenotype of HCC." (PMID 36313762, 2022). "Low-dose DB (12.5 μM) downregulated PD-L1 to activate NLRP3-mediated pyroptosis, and inhibited cancer stem cells (CSCs) properties, to sensitize cisplatin-resistant GC (CR-GC) cells to cisplatin." (PMID 33579380, 2021). "The proposed pathway elicits NLRP3 as a therapeutic target to reverse canonical STAT3 mediated mechanisms of cancer promotion." (PMID 34531850, 2021). "These seemingly contradictory functions of the NLRP3 inflammasome in tumors are likely time, context, tissue, and cancer specific." (PMID 33649199, 2021). "Despite the great interest it has garnered over the last few years, the molecular mechanism of NLRP3 inflammasome action remains poorly understood, especially its role in cancer." (PMID 34540671, 2021). "This evidence implies that zerumbone exerts anti-inflammatory and anti-cancer activities by attenuating the activation of NLRP3 inflammasome." (PMID 34045963, 2021). "In this review, we will discuss the NLRP3 inflammasome as a double-edged sword in cancer, as it can have both protumorigenic and antitumorigenic effects not only in different cancers but also in a tissue-specific manner." (PMID 34064909, 2021). "In this review, we discuss the role of NLRP3 in the development and progression of cancer, offering a detailed summary of NLRP3 inflammasome activation (and inhibition) in the pathogenesis of various forms of cancer." (PMID 34064909, 2021). "Our study found that a deletion of NLRP3 in human HCC SK-Hep1 Luc cells represses cancer development and metastasis of HCC cells as well as enhances the sensitivity of NK cell cytotoxicity in vitro and in vivo." (PMID 34502191, 2021). "NLRP3 inflammasome activation had been shown to activate cancer stem cells (CSCs) leading to self-renewal and acceleration of HNSCC progression." (PMID 34660289, 2021). "The pro-tumorigenic role of the NLRP3 inflammasome has been reported in several different cancers such as breast, melanoma, head and neck squamous cell carcinomas, colorectal, lung, and hepatocellular carcinomas." (PMID 34684819, 2021). "Once activated, NLRP3 inflammasome induces the release of pro-inflammatory cytokines IL-1β and IL-18, which can contribute to cancer progression." (PMID 34681768, 2021).
cancer (continued). "The impact of NLRP3 in the development of immunosenescence and the immune response should be considered in adoptive cellular immunotherapy strategies to treat cancer patients." (PMID 34685542, 2021). "The NLRP3 inflammasome has been identified as an oncogene in genomic analyses of non-small cell lung cancer, and in breast, head, and neck cancers." (PMID 34885171, 2021). "Recently, more attention has been given to the potential application of NLRP3 inhibitors for the treatment of cancer." (PMID 34681768, 2021). "This is bound to widen therapeutic modalities for patients suffering from NLRP3-mediated metabolic and neurodegenerative diseases as well as certain cancers, where there is a tremendous unmet therapeutic need." (PMID 34443594, 2021). "For example, a pan-cancer study showed that there was a significant different expression of NLRP3 in 15 different cancers, and it was used as an independent posterior factor of SKCM." (PMID 34899842, 2021). "Since the NLRP3 inflammasome plays an important role not only in hematological diseases but, also, in many inflammatory diseases and cancers, it has gained special interest as a promising therapeutic target." (PMID 33525345, 2021). "The effects of the NLRP3 inflammasome on tumorigenesis have been shown to vary from cancer to cancer." (PMID 34439930, 2021). "By modulating the AMPK/mTOR signaling cascade with consequent suppression of NLRP3 inflammasome activation, metformin is capable of impeding cancer progression in a promising fashion." (PMID 34443594, 2021). "It has been shown that the inflammasome receptor NLRP3 recognizes a diverse set of pro-inflammatory stimuli including metabolites that are actively secreted in an extracellular microenvironment during cancer expansion." (PMID 34070682, 2021). "This study aims to establish the role of accumulated macrophage-activated NLRP3-IL-18-eosinophil mechanistic pathway in promoting several characteristics of pancreatic malignancy in CP." (PMID 34183442, 2021). "The clinical relevance of the NLRP3 inflammasome in multiple forms of cancer highlights its therapeutic promise as a molecular target." (PMID 34064909, 2021). "This is further consistent with the observation that several cancer types exhibit an upregulation in the expression of NLRP3 relative to their benign tissue counterparts." (PMID 34638239, 2021). "In conclusion, we, for the first time, analyzed the effect of the antibiotic doxycycline on the regulation of NLRP3 activation in cancer cells." (PMID 34577552, 2021). "Meanwhile, cancer cells can directly or indirectly affect the key molecules in the NLRP3 pathway, thus leading TAMs reprogramming toward a pro-inflammatory state." (PMID 35047512, 2021). "These should be complemented by ex vivo studies of NLRP3 activity in cancer patients treated with the increasingly specific BTK inhibitors or biomaterial from healthy volunteers and XLA patients." (PMID 33718366, 2021). "As opposed to its reported role in the innate immune system, NLRP3 inflammasome-mediated regulation of adaptive immune responses to cancer has been less well-described." (PMID 34638239, 2021). "Currently, numerous studies have revealed that NLRP3 inflammasome has a crucial role in the pathogenesis of many diseases, such as cancer, cardiovascular diseases, and metabolic diseases." (PMID 35047512, 2021). "The NF-κB signaling pathway regulates NLRP3 and caspase-1 in the proliferation and migration of various cancer cells." (PMID 34239588, 2021). "Many studies suggested that inhibition or inactivation of NLRP3 inflammasome plays an antitumor role in many cancers." (PMID 34211462, 2021). "It has been reported that NLRP3 inflammasome has different effects in different malignancies and is considered a double-edged sword against cancer." (PMID 34925460, 2021).
cancer (continued). "Studies have shown that NLRP3 increased expression and/or activity in several types of cancer, such as melanoma, head and neck squamous cell carcinoma, lung squamous cell carcinoma, pancreatic, and bladder cancer." (PMID 33918290, 2021). "The clinical relevance of NLRP3-inflammasome in multiple forms of cancer highlights its therapeutic promise as a molecular target." (PMID 34070682, 2021). "NLRP3 inflammasome is reported to be abnormally expressed and activated in malignancies such as cancer, favoring its progression." (PMID 34681768, 2021). "A recent study demonstrated that activated NLRP3 significantly promoted the plasma levels of cytokines in patients with cancer." (PMID 34178667, 2021). "The NLRP3 inflammasome is one of the critical components of the innate immune system and it plays an important role in cancers." (PMID 34454534, 2021). "Our findings highlight the potential of antibiotics as regulators of the NLRP3 inflammasome as a possible approach to avert cancer inflammation." (PMID 34577552, 2021). "High NLRP3 level correlated with the advanced TNM classification of malignant tumors, the occurrence of distant metastasis, vascular invasion, and positive lymph nodes." (PMID 33821998, 2021). "On the other hand, knockdown of NLRP3 expression inhibited the growth of cancer cells and reduced caspase-1 activation and IL1β maturation." (PMID 34064909, 2021). "Further studies showed that the exacerbation of NLRP3 inflammasome activation by ABHD5 deficiency, provides a positive feedback loop to promote cancer progression by preferentially secrete the proinflammatory cytokine IL-1β." (PMID 32867817, 2020). "In conclusion, we provide compelling, new evidence for a direct involvement of SPHKs in macrophage NLRP3 inflammasome activation and provide a rationale for therapeutic targeting these kinases in cancer and inflammation." (PMID 32630814, 2020). "Herein, we briefly outline the mechanisms underlying the activation of NLRP3 and AIM2 inflammasomes, as well as their crosstalk with autophagy in the context of cancer." (PMID 32703253, 2020). "NLRP3 inflammasome have been shown to promote the development of several cancers, where most studies were focused on proliferation, survival, metastasis, angiogenesis, and immunosuppression." (PMID 32733479, 2020). "In the last two years, a couple of studies demonstrated a role of NLRP3 in immune suppression in cancer." (PMID 33116132, 2020). "The function of NLRP3 inflammasome in human cancers is rather a conflicting topic, where there is evidence of a protective anti-tumorigenic effect as well as a pro-tumorigenic role in different types of cancer." (PMID 32733479, 2020). "In the present study, we further revealed that the exacerbation of NLRP3 inflammasome activation by ABHD5 deficiency, provides a positive feedback loop to promote cancer progression by preferentially secrete the proinflammatory cytokine IL-1β." (PMID 32867817, 2020). "Two other nutraceuticals isolated from Chinese herbs are promising candidates for counteracting cancer through the activation of the NLRP3 pathway." (PMID 32650482, 2020). "FGF1 activation is mediated via the PI3K-Akt signaling pathway that lies upstream of mTOR, which is related to autophagy, apoptosis and metabolism of cancer cells, as well as the NLRP3-mediated inflammatory response." (PMID 32615540, 2020). "The involvement of the NLRP3 inflammasome in several inflammation-related diseases, including cancer, provided it as an attractive potential target in designing new drugs for treatment." (PMID 32733479, 2020). "It has been shown that NLRP3 inflammasome plays an important role in the development of many cancer types." (PMID 32974137, 2020). "To date, the Nod–Like Receptor Protein 3 (NLRP3) inflammasome has been well studied and its involvement has been established in different cancer diseases." (PMID 33014808, 2020).
cancer (continued). "Activation of NLRP3 also leads to release of active interleukin-18 (IL-18), which has been found to mediate painful conditions such as muscle pain, cancer-induced bone pain and neuropathic pain." (PMID 32973552, 2020). "Animal and cell culture studies showed that arsenic trioxide and other arsenic compounds inhibited NLRP3 inflammasome, caspase-1, and IL-1β inflammatory signaling, and played a major role in its anti-cancer effects." (PMID 32313131, 2020). "In this review, we summarize these contradictory roles of NLRP3 inflammasome in cancer, shed the light on oncogenic signaling leading to NLRP3 activation and IL-1β production and outline the current knowledge on therapeutic approaches." (PMID 32733479, 2020). "The tumorsphere formation assay was used to assess stem cell-like characteristics of cancer cell lines after modulation of the NLRP3 inflammasome." (PMID 33613529, 2020). "Altogether, these pieces of evidence show the diverse roles that NLRP3 has in cancer pathology, revealing the potential of this inflammasome as a therapeutic target." (PMID 32604771, 2020). "Here, we discuss the structure and activation pathways of NLRP3, and provide a brief updated review on the most recent research investigating its opposing roles in cancer." (PMID 32733479, 2020). "This evidence illustrates that the activated NLRP3 inflammasome re-localizes within the cell-driven mitochondrial dysfunction in cancer cells, resulting in metabolic reprogramming and cancer progression." (PMID 33613533, 2020). "Accumulating evidence suggests that the NLRP3 inflammasome influences the pathogenesis of cancer by regulating immune responses, cell proliferation, and death." (PMID 32303673, 2020). "Recent progress in the action of NLRP3 witnessed remarkable adeptness in paralyzing immune cells dispatched to eliminate cancer by immunosuppressive secretions." (PMID 33613533, 2020). "A list of compounds targeting NLRP3 inflammasome either indirectly or directly and their therapeutic potential in cancers." (PMID 32733479, 2020). "Excessive activation of NLRP3 inflammasome can contribute to development of inflammatory diseases and cancer." (PMID 33163006, 2020). "For instance, E2 has been shown to significantly reduce NLRP3 inflammasomes in allergic airway inflammation and mediated a marked reduction of inflammation and cancer progression in patients via estrogen receptor beta." (PMID 32645874, 2020). "Similar results were observed in a model of colorectal cancer, where TAMs surrounding the cancer have strong NLRP3 and IL-1β expression, as well as inflammasome activation." (PMID 32883606, 2020). "•Enhanced NLRP3 inflammasome activation worsens neurodegenerative and metabolic conditions as well as cancer." (PMID 32883606, 2020). "Altogether, several lines of evidence have emerged supporting the pro-tumourigenic role of NLRP3 inflammasome in cancer." (PMID 33116132, 2020). "Taken together, these findings indicate that gAcrp suppresses activation of the NLRP3 inflammasome in cancer cells." (PMID 32155890, 2020). "This connection between NLRP3, bowel diseases, and cancer is multifaceted and the resulting inflammation and cytokine secretion (namely IL-18) can be protective against tumor growth." (PMID 32098318, 2020). "Despite the well-characterized crucial functions for NLRP3 inflammasome in the immune system, their roles in cancer remain rather complicated and elusive." (PMID 32733479, 2020). "NLRP3 using conditional knockout models and pharmacological activators or inhibitors is needed to decode the precise mechanisms of NLRP3 activity in cancer." (PMID 33613533, 2020). "Coptisine, a natural compound extracted from Coptis chinensis, exerted potent anti-cancer effects through activation of autophagy or NLRP3 inflammasomes." (PMID 32703253, 2020). "IL-1β production contributes to cancer development and progression but also limits the 5-FU anticancer effect through NLRP3 inflammasome activation in MDSC7,28–30." (PMID 31217433, 2019).